RNU6-971P (RNA, U6 small nuclear 971, pseudogene)
Gene: Small nuclear RNA gene on chromosome 17 (43,473,585 to 43,473,690, forward strand). Ensembl gene ENSG00000252729.
Homologues: Orthologues: chimpanzee U6 (100% identical), macaque U6 (95% identical), dog U6 (82% identical), rabbit U6 (72% identical), mouse Gm26099 (68% identical). Paralogues in human: RNU6-338P (92% identical), RNU6-49P (92% identical), RNU6-1124P (91% identical), RNU6-12P (90% identical), RNU6-13P (90% identical), RNU6-25P (90% identical), RNU6-29P (90% identical), RNU6-32P (90% identical), RNU6-33P (90% identical), RNU6-41P (90% identical), RNU6-820P (90% identical), RNU6-1 (89% identical), and 1288 more.